CD164L2 (CD164 molecule like 2)
Synonyms: EAPG6122; UNQ6122
Tractability: Antibody: UniProt predicts a signal peptide or a membrane-spanning region; the Human Protein Atlas places it where antibodies can reach.
Gene: Protein-coding gene on chromosome 1 (27,379,176 to 27,383,333, reverse strand). Ensembl gene ENSG00000174950.
Subcellular location: Membrane
Subcellular location (Human Protein Atlas): Cytosol; Plasma membrane
Gene Ontology:
Cellular component: cytoplasmic vesicle; membrane
Genetic constraint (gnomAD): Loss-of-function variants: 21 observed, 23.85 expected, observed/expected ratio (o/e) 0.88, 90% interval 0.62 to 1.27. The upper end of that interval is the gene's LOEUF score, 1.27, which puts it in group 5 of 6, group 1 being the genes least tolerant of losing a copy. Missense variants: 230 observed, 224.26 expected, observed/expected ratio (o/e) 1.03, 90% interval 0.92 to 1.14. Synonymous variants: 92 observed, 89.95 expected, observed/expected ratio (o/e) 1.02, 90% interval 0.86 to 1.22.
Homologues: Orthologues: chimpanzee CD164L2 (99% identical), dog CD164L2 (87% identical), guinea pig CD164L2 (86% identical), pig CD164L2 (84% identical), mouse Cd164l2 (81% identical), rat Cd164l2 (69% identical), zebrafish cd164l2 (32% identical), Drosophila melanogaster vsg (18% identical). Paralogues in human: CD164 (29% identical), TMEM123 (17% identical).
Diseases named in the same sentence as CD164L2 in open-access papers:
CD164L2 is named in the same sentence as 3 diseases in open-access papers, as found by Europe PMC text mining. Sharing a sentence is not in itself a finding about the gene and the disease. The quoted sentences say what the papers report.
breast carcinoma (1 paper, 2018). "Notably, four lncRNAs (lnc-RPRD2-3:1, lnc-KCNA5-3:4, lnc-CFP-1:1 and lnc-CD164L2-1:1) correlated strongly with the mutation status of IGF2R, a tumor suppressor commonly mutated in human liver and breast cancer." (PMID 29416609, 2018).
prostate carcinoma (1 paper, 2018). A carcinoma that arises from epithelial cells of the prostate gland. "Lnc-CD164L2 has a gene locus resides in the intronic region of the protein coding gene CD164, which has been found to act as a metastasis promoter in prostate cancer." (PMID 29416609, 2018).
tumor (1 paper, 2018). "Notably, stage-dependent correlation was observed between the expression level of two lncRNAs, lnc-FABP6-4:1 and lnc-CD164L2-1:1, and tumor grade, a grading system that characterizes level of differentiation of malignant cancer cells." (PMID 29416609, 2018).